AXL (AXL receptor tyrosine kinase)
Diseases named in the same sentence as AXL in open-access papers (continued):
Sharing a sentence is not in itself a finding about the gene and the disease.
cancer (continued). "HSF1 inhibition by using HSF1 shRNAs or KRIBB11 decreased the expression of HSF1 downstream proteins, such as HSP70 and HSP27, and also decreased the expression of HSP90/HSP70/BAG3 client proteins, such as BCL2, MCL1, EGFR, MET, and AXL, causing apoptosis of EGFR-TKI-resistant cancer cells." (PMID 34203709, 2021). "Crizotinib is known to target and decrease AXL phosphorylation in other cancer types." (PMID 34577598, 2021). "Most research about AXL focused on cancer and cell survival." (PMID 33954117, 2021). "AXL is a well-known marker of mesenchymal differentiation in multiple types of cancer." (PMID 34359798, 2021). "Moreover, AXL also plays key roles in metastasis, invasion and cancer proliferation, as well as EMT." (PMID 33207077, 2021). "Small molecule inhibitors of AXL render MDR cancer cells sensitive to NK cells and CTL." (PMID 34263254, 2021). "Further, the combination of EGFR inhibitor (erlotinib) and GAbsiAXL synergistically enhanced apoptosis and inhibited cancer cell migration, demonstrating that RNA-based inhibition of AXL in the combination of chemotherapies may be beneficial in NSCLC." (PMID 33740988, 2021). "AXL and its ligand, GAS6, have been implicated in metastasis and tumorigenesis of various cancers." (PMID 34831142, 2021). "It is suggested that targeting AXL has great therapeutic potential and may disrupt Wnt/α-catenin and TGFâR signaling and spherical formation, thereby increasing resistance to cancer and its progression." (PMID 34926461, 2021). "Our findings that AXL mediates the oncogenic signaling of p85β provide further support for targeting AXL as a cancer treatment and suggest that PIK3R2 amplification could serve as a biomarker for the efficacy of AXL inhibitors." (PMID 32385243, 2020). "This confirmed earlier reports in other cancer types that AXL is regulated by YAP/TAZ." (PMID 32148495, 2020). "Thus, we concluded that the ALDH1A1 and SLUG axis regulated by AXL is involved in tumourigenicity and stemness, and that cancer prevention with EGCG mediates inhibition of the AXL/ALDH/SLUG axis." (PMID 32051483, 2020). "Furthermore, GAS6 activation of AXL has been suggested to play a less dominant role in settings where AXL is overexpressed, such as in cancer." (PMID 31917795, 2020). "Inhibition of AXL by TP-0903 may potentially reduce cancer cell metastasis, reverse resistance to immunotherapy and targeted therapy, and activate the anti-cancer immune response." (PMID 32448366, 2020). "In addition, both MET and AXL have been reported to be intrinsically linked to epithelial‐mesenchymal transition (EMT), promoting cell survival and cancer metastasis." (PMID 34766112, 2020). "Given these functions of AXL, it is not surprising that AXL plays a role in cancer progression, and indeed AXL has been implicated in a wide variety of malignancies from solid to liquid tumors." (PMID 32148495, 2020). "Our results suggest that targeting c-ABL with the clinically approved cancer drug imatinib alone or in combination with AXL inhibitors could be an effective therapeutic intervention in EAC." (PMID 32922529, 2020). "Furthermore, AXL signaling in tumors promotes cancer stem cell-like phenotypes, drug resistance, metastasis, and EMT." (PMID 33374832, 2020). "The abnormal expression and activation of AXL provides cancer cells a survival advantage by activating the phosphatidylinositol 3-kinase (PI3K)/mammalian target of rapamycin (mTOR) and MAPK pro-survival pathways as well as pathways related to cell growth, migration, and invasion." (PMID 33283192, 2020). "Among the 3 TAM family members, AXL has been an attractive target for the treatment of cancer." (PMID 32042425, 2020). "Combination therapy with AXL inhibitors has been found effective for treating various cancers." (PMID 33283192, 2020). "The expression of MER, TYRO3, and AXL were profiled among multiple human cancer cells." (PMID 32042425, 2020).
cancer (continued). "Moreover, AXL acts as a crucial regulator of cancer-related EMT; particularly in HCC, the cooperation between Gas6/Axl and TGF-β signaling pathways appears to be crucial in differentiation, EMT, and the advancement of invasion." (PMID 32517019, 2020). "Certainly, BGB324, due to its high selectivity for AXL, is the drug that has mainly produced significant results in terms of growth inhibition; in addition, it is the only specific AXL inhibitor to be involved in clinical trials for the treatment of several cancers." (PMID 33182542, 2020). "AXL signaling activates downstream MAPK/ERK and PI3K/Akt pathways, which are known to drive cell survival, proliferation, migration and invasion, both of which are crucial for cancer progression and associated with poor patient outcomes." (PMID 35582229, 2020). "While many studies show that the role of AXL is closely associated with EMT in many types of cancer, the role of AXL in VM formation has not been investigated." (PMID 33374832, 2020). "At present, it remains unclear how cancer cell migration and invasion are regulated by cabozantinib via inhibition of AXL and MET." (PMID 32055714, 2020). "AXL’s dysregulation promotes drug resistance in many cancer contexts and not only." (PMID 33182542, 2020). "Together, these results suggest that, as an alternative to direct inhibitors of AXL, elucidation of the mechanisms underlying how AXL is regulated at the mRNA level may help develop novel AXL-targeting approaches for cancer treatment in the future." (PMID 31729427, 2019). "However, gilteritinib has inhibitory activity against AXL, which has cancer immunosuppressive activity." (PMID 31692922, 2019). "Aberrant AXL expression also affects migration and invasiveness of cancer cells." (PMID 31694201, 2019). "At least 19 AXL TKIs are in phase I/II or preclinical development for cancer therapies." (PMID 31336846, 2019). "In our previous studies, we have found that AXL not only is crucial in cancer cells invasiveness but also may play an important role in chemo-resistance." (PMID 31729427, 2019). "AXL not only is crucial in the in vitro invasiveness but also may play an important role in cancer progression in patients." (PMID 31729427, 2019). "Then, we highlight recent strategies for targeting AXL in the treatment of cancer.AXL-targeted drugs, either as single agents or in combination with conventional chemotherapy or other small molecule inhibitors, are likely to improve the survival of many patients." (PMID 31684958, 2019). "Of note, only over-expression and/or activation of the AXL protein, but not AXL gene mutations, have been reported in cancer patients." (PMID 31729427, 2019). "In conclusion, we found that ALK signaling-independent AXL overexpression associated with EMT features and CSC properties was commonly involved in the maintenance of cancer survival, and was critical in intrinsic and acquired resistance to first-and second-generation ALK-TKIs." (PMID 29930762, 2018). "Importantly, transcriptomics analysis of the screened 941 cancer cell lines revealed that high AXL and TYRO3 mRNA levels predict both resistance to necroptosis and low RIPK3 mRNA levels, but not those of RIPK1, MLKL, or any other pro-necroptotic genes." (PMID 30157175, 2018). "As c‐MYC has been shown to play a role in cancer therapy drug resistance, we investigated whether AXL‐dependent epirubicin resistance involves regulation of c‐MYC expression in EAC cells." (PMID 30353671, 2018). "Inhibition of AXL and its downstream proteins is a novel approach in treating cancers." (PMID 30386383, 2018). "AXL and HSP90 inhibitors may be effective against a drug-tolerant cancer cell subpopulation that has caused relapse and drug resistance in patients." (PMID 29930762, 2018). "ALK signaling-independent AXL overexpressed in drug-tolerant cancer cell subpopulations with EMT and CSC features may be commonly involved commonly involved in intrinsic and acquired resistance to ALK-TKIs." (PMID 29930762, 2018).
cancer (continued). "Moreover, high AXL/TYRO3 levels are potential predictors/biomarkers for loss of RIPK3 expression and necroptosis resistance in cancer." (PMID 30157175, 2018). "Overall, these findings suggest that AXL/TYRO3 overexpression, frequently seen in cancers, promotes the loss of RIPK3 expression and escape from necroptosis, which may be reversed upon inhibition of these kinases." (PMID 30157175, 2018). "AXL is targeted by several miRNAs, and its dysregulation has a role in various cancers." (PMID 30386383, 2018). "To investigate whether AXL can be cleaved by γ-secretase, we first treated various types of cancer cell lines with DAPT, a known inhibitor of γ-secretase." (PMID 28034848, 2017). "Similarly, activation of fibroblasts at the metastatic niche is mediated by AXL, expressed by mesenchymal circulating cancer cells homing to the niche, which has been shown to be necessary for metastatic colonization and MET." (PMID 28750639, 2017). "In addition, elevated AXL expression has been found to be correlated with adverse prognosis and distant metastasis in some cancers." (PMID 28455956, 2017). "Axl receptor tyrosine kinase is involved in the tumorigenesis and metastasis of many cancers." (PMID 28720772, 2017). "The substantial amount of AXL-ICD present in the nuclei of cancer cells immediately suggests that AXL-ICD could play a role in the nucleus —possibly negative regulation of the expression of cancer-related genes." (PMID 28034848, 2017). "As we have demonstrated that intramembrane cleavage of AXL-FL actively occurs in cancer cells, we wondered whether the γ-secretase–mediated processing of AXL plays a role in the drug resistance of TKIs." (PMID 28034848, 2017). "We think that AXL is a key stimulator of cell softening of cancer cells and cancer progression." (PMID 29259259, 2017). "In that regard, proteolytic cleavage of AXL by secretases could potentially play an essentially anti–drug-resistant role in cancer." (PMID 28034848, 2017). "It is important to note that AXL stimulates the sphere-forming ability, tumourigenicity and expression of CD4432,33, and that the elevating the miRNA-processing enzyme Dicer increased the levels of AXL, and reduced the cancer stem-like property in breast cancer." (PMID 29259259, 2017). "AXL has been reported to be ectopically expressed or overexpressed in a multitude of human cancers." (PMID 28551766, 2017). "Collectively, these data indicate that AXL may function as a potent oncogene that can improve resistance to conventional and targeted cancer therapies." (PMID 28455956, 2017). "This led us to the question whether self‐sustaining or cancer‐initiating cells could be identified by overcoming challenging conditions like serum deprivation and/or treatment with AXL/MET inhibitor BMS777607." (PMID 28675785, 2017). "The activation of AXL contributes to resistance to EGFR-TKI in multiple types of cancers." (PMID 27590506, 2016). "AXL signaling in cancer is regulated by genetic, epigenetic, and microenvironmental factors." (PMID 27834845, 2016). "Both EGFR and AXL play important role in cancer progression and are related to poor prognosis." (PMID 27590506, 2016). "Thus, through both MET and AXL inhibitions, Cabozantinib was shown to induce cancer shrinkage and cell growth reduction in medullary thyroid and prostate carcinoma." (PMID 26859576, 2016). "AXL expression appears to increase during cancer progression and metastasis." (PMID 27834845, 2016). "Recently, it has been demonstrated that increased AXL expression could contribute to drug resistance in cancer cell lines." (PMID 26859576, 2016). "Collectively, these studies suggest that AXL may be a marker and functional driver of the cancer stem cell phenotype." (PMID 27834845, 2016). "Moreover, E1A has been shown to downregulate RTKs, such as EGFR, HER2/neu or AXL, and accumulating evidence has indicated that RTKs play important roles in cancer progression." (PMID 27590506, 2016).
cancer (continued). "Recently, inhibitor targeting AXL was validated as a novel treatment candidate in cancer therapy." (PMID 26942465, 2016). "In cancer, AXL signaling can be activated by GAS6 in an autocrine or paracrine manner." (PMID 27834845, 2016). "In addition to EGFR-TKI, AXL also induced resistance to other targeted therapies or chemotherapy in multiple types of cancer." (PMID 27590506, 2016). "Furthermore, overexpression of AXL has been shown to promote cancer cell proliferation and invasion and correlate with poor patient prognosis." (PMID 26356563, 2015). "Furthermore, we applied yuanhuadine (YD), an antitumor agent, to confirm the effect of enhancing AXL degradation on cancer cell proliferation." (PMID 25760142, 2015). "Taken together, those previous studies suggest that AXL may be a key signaling node regulating several biological processes during tumorigenesis and cancer progression." (PMID 26573603, 2015). "Alternatively, since hMAb173 induces AXL endocytosis, an antibody-drug conjugate (ADC) could be designed to bring a cytotoxic drug into AXL expressing cancer cells, leading to selective cell killing." (PMID 26356563, 2015). "These key observations suggest that inhibition of TAM/AXL activity could in fact have additional anti-cancer activity through NK cell potentiation against metastatic disease." (PMID 25337673, 2014). "In addition, specific miRs (microRNAs) that target the 3′-UTR of the AXL gene have been identified in several cancer cell lines." (PMID 25337673, 2014). "AXL is expressed in various normal organs and cells and over-expressed in several cancers." (PMID 25110867, 2014). "AXL expression was found to be correlated with cancer poor prognosis." (PMID 25110867, 2014). "Similar to MET, AXL is commonly up-regulated in drug resistant cell lines and cancers." (PMID 25551830, 2014). "AXL has been reported to be overexpressed or ectopically expressed in a multitude of cancers." (PMID 25337673, 2014). "The expression difference of AXL between benign and malignant tumors is still unclear." (PMID 25551830, 2014). "The molecular mechanisms constituting overexpression of AXL in cancer are still elusive." (PMID 23077658, 2012). "Consequently blocking the Gas6/AXL signaling pathway represents an attractive therapeutic strategy in cancer." (PMID 23077658, 2012). "Increased expression of AXL is a recurrent characteristic of cancer cells." (PMID 22141136, 2011). "Cancers with active GAS6-AXL pathways may benefit from PI3K or AXL inhibitors to reduce metastasis." (PMID 40332008, 2025). "However, some studies indicate that AXL inhibition can sensitize cancer cells to other treatments." (PMID 39924521, 2025). "Therefore, in a cancer pathological setting, AXL expression may largely favor the disease’s progression, and as a consequence, AXL inhibition could constitute a potential likely therapeutic target." (PMID 38391974, 2024). "In light of the oncogenic functions of AXL, clinical trials targeting AXL with different means, such as small molecular inhibitors, antibody-drug conjugates, and monoclonal antibodies have been conducted to evaluate the therapeutic potential of AXL inhibition for anti-cancer treatment." (PMID 38310091, 2024). "Since GAS6/AXL interaction has been described to trigger various signaling pathways in cancer cells, including PI3K-AKT, NFκB, RAS-MEK-ERK, SRC-FAK and JAK-STAT 8; it might be interesting to further elucidate the downstream mechanisms of action of sdAb20-Fc in AML." (PMID 38773967, 2024). "TMPRSS2 and AXL was down-regulated often in cancers but SCARB1 showed the reverse trends, while all of three was shown to be expressed abnormally more frequently than ACE2 and NRP1, which could not provide an expression patten possibly due to their limited situations." (PMID 36875081, 2023). "Therefore, monitoring AXL expression on the surface of cancer cells could become a companion biomarker of AXL targeted therapy efficacy." (PMID 38132919, 2023).
cancer (continued). "Monoclonal anti-AXL antibodies could suppress the growth and metastasis of variety of cancers." (PMID 37475048, 2023). "As abnormal expression and activation of AXL may promote chemotherapy resistance, cancer cell proliferation, invasion, and metastasis, blocking AXL pathways may enhance the sensitivity of cancer cells to cytotoxic agents and help to overcome the problem of resistance to EGFR TKIs." (PMID 36892745, 2023). "Additionally, markers of cellular senescence CDKN2/p16ink4a and CDKN1A/p21 did not change between treatment groups in the RPPA analysis, while AXL, a known dormancy initiator in the context of PCa bone metastasis, increased in cancer cells treated with B-CM in the RPPA analysis." (PMID 36138750, 2022). "Our data also indicate that this redelivery of AXL to the plasma membrane might be specifically responsible for the sustained activation of AKT to promote cancer-cell migration and invasion, especially that the plasma membrane is a major site of activation of this effector kinase." (PMID 35622156, 2022). "Therefore, AXL activation in cancer cells and stromal cells could also promote disease progression by acting on angiogenesis, fibrosis, immune evasion, and hypoxia." (PMID 35158733, 2022). "Systemic AXL inhibition may enhance the efficacy of cancer therapy via multiple mechanisms." (PMID 36261437, 2022). "Therefore, targeting AXL for inhibition is an approach worth considering in cancer therapy." (PMID 35356198, 2022). "The existence of a cell-intrinsic program through which AXL-positive/Erlotinib-resistant cells emerge infers the need of treating tumors harboring EGFR-oncogenic mutations upfront with combinatorial treatments targeting both AXL-negative and AXL-positive cancer cells." (PMID 34254585, 2021). "Therefore, the upregulation of AXL induced by doxorubicin treatment or present in doxorubicin‐resistant cancer cells and YAP‐dependent AXL expression suggests that YAP/TAZ activation may occur by doxorubicin treatment alone." (PMID 33207077, 2021). "However, this method appears to be highly ineffective for AXL inactivation in cancer cells." (PMID 34948046, 2021). "Therefore, AXL inhibition represents an attractive treatment option in these cancers." (PMID 34877810, 2021). "Furthermore, AXL is known to mediate cancer cell phenotypic plasticity and EMT47,48, suggesting that upregulation may be related to the morphological shift of resistant H1975 cells to a mesenchymal-like state." (PMID 33712563, 2021). "However, ROS signaling activates AXL, which diminishes cytotoxicity against cancer cells." (PMID 33921908, 2021). "Importantly, as AXL has been identified as a drug resistance mediator to PI3K inhibition in several cancer types, pan-TAM inhibition may be a sensible approach to preventing resistance in settings even beyond HNSCC; this is a key area for future study." (PMID 33059733, 2020). "This ‘initial survival’ of cancer cells from targeted therapy against driver oncogenes has recently been highlighted in epidermal growth factor receptor (EGFR)-mutated tumors, and the Notch-3/β-catenin pathway or AXL has been shown to play a key role in this survival." (PMID 31900393, 2020). "In contrast to its role in proliferation, AXL may control quiescence and cancer cell dormancy." (PMID 31694201, 2019). "Thus, AXL has emerged as a novel therapeutic target for cancer." (PMID 28034848, 2017). "Indeed, activation of AXL by GAS6 was demonstrated in various cancer models." (PMID 28118606, 2017). "Pharmacological inhibition of the kinase activity of AXL has been demonstrated to counteract drug resistance in tyrosine kinase inhibitors (TKIs) in vitro and in vivo, which is an approach that is currently being tested in clinical trials for several types of cancers." (PMID 28034848, 2017).